CGAS (cyclic GMP-AMP synthase)
Diseases named in the same sentence as CGAS in open-access papers (continued):
Sharing a sentence is not in itself a finding about the gene and the disease.
tumor (continued). "To further investigate the functional characterization of cGAS and STING in the tumor microenvironment, we utilized the TISIDB database to explore the correlation between CGAS and STING1 expressions and immune cell abundances." (PMID 40735041, 2025). "On the one hand, metal ions themselves can modulate the immune status in several ways, e.g. Mn metal can both activate the cGAS–STING pathway and alleviate intra-tumor hypoxia based on a Fenton-like response." (PMID 40486836, 2025). "Radiation also releases tumor DNA that activates the cGAS-STING pathway within dendritic cells and tumor cells, driving type-I interferon programs that promote cross-presentation and prime tumor-specific CD8 T cell responses." (PMID 41194129, 2025). "By regulating the interaction between YAP1 and the cGAS-STING pathway, we demonstrate that inhibition of YAP1 can overcome immune suppression and enhance anti-tumor immunity, offering new therapeutic strategies for HCC treatment." (PMID 40918140, 2025). "The targeted drug release induced DNA damage in the tumor cells, activated the cGAS-STING pathway, and increased the infiltration of DCs and CD8+ T cells in the TIME, resulting in enhanced anti-tumor immune response." (PMID 39757995, 2025). "The cGAS–STING pathway can exert both antitumor and protumor effects depending on the tumor’s genetic background and microenvironmental context." (PMID 41204180, 2025). "In a word, our findings confirmed that RT activated the cGAS‐STING pathway, triggered type I IFN response, induced ICD in tumor cells, and upregulated tumor cell surface MHC‐I, thus priming anti‐tumor immunity and restoring immune recognition." (PMID 40470716, 2025). "This activates the cyclic GMP-AMP synthase-stimulator of interferon response cGAMP interactor (cGAS-STING) pathway, which plays a critical regulatory role in tumor immunity." (PMID 40433389, 2025). "This activates the cyclic GMP‐AMP synthase (cGAS)‐stimulator of the IFN gene (STING) signaling pathway, thereby enhancing anti‐tumor immunotherapy through dendritic cell‐T cell‐dependent functions." (PMID 40344511, 2025). "This therapeutic strategy leverages the cGAS–STING signaling cascade, which detects aberrant cytoplasmic DNA and induces inflammatory responses, thereby reshaping the tumor immune landscape." (PMID 40977697, 2025). "These microneedles enhance antitumor immunity by activating the cGAS‐STING pathway, suppress tumor growth, reduce metastasis, and promote wound healing." (PMID 40042034, 2025). "One possibility is that most tumor cells are killed shortly after CTX treatment and that the consequent released dsDNA is taken up by host APCs to activate APC-intrinsic cGAS." (PMID 40227734, 2025). "Tumor samples were collected from the patients before receiving NACI treatment, and expression levels of cGAS and STING in tumor cells were evaluated by performing immunohistochemistry." (PMID 40735041, 2025). "To explore anti‐tumor mechanism, we evaluated TME changes after EB@MPCM+Laser treatment, including cGAS‐STING pathway related proteins, immune cells and cytokines." (PMID 39792614, 2025). "These materials have been shown to activate the cGAS-STING/NF-κB signaling pathway through TLR4, thereby promoting DC maturation and inducing the secretion of IL-6, thus inhibiting tumor growth." (PMID 40432108, 2025). "This combined treatment induces significant DNA damage, thereby activating the cGAS-STING pathway and remodeling the tumor immune microenvironment." (PMID 41438738, 2025). "The cyclic GMP–AMP synthase (cGAS)–stimulator of interferon (IFN) genes (STING) pathway emerges as a dual‐functional role in urologic malignancies, exhibiting context‐dependent tumor‐suppressive and pro‐tumorigenic activities." (PMID 41275427, 2025). "The cGAS/STING pathway is heterogeneous, with tumor-suppressive or tumor-promoting activity, which offers great potential for the development of antitumor treatments." (PMID 39975558, 2025).
tumor (continued). "IL6-induced mtDNA leakage and activation of the cGAS-STING pathway help EC cells evade immune detection, promoting tumor progression." (PMID 39949780, 2025). "This leads to cGAS-STING-dependent IFN-I secretion, improving tumor antigen uptake, DC maturation, and cross-priming of CD8+ T cells." (PMID 41246345, 2025). "NSUN2 also enhances m5C modifications on three prime repair exonuclease 2 mRNA, promoting its expression, inhibiting cGAS/STING activation, and facilitating tumor development." (PMID 41463199, 2025). "Methylglyoxal enhances radiotherapy-induced ICD through cGAS-STING pathway activation, demonstrating potent local tumor control and abscopal effects when combined with anti-PD-1 therapy in advanced CRC models." (PMID 41181090, 2025). "Tumor-derived antigens in the tumor microenvironment can activate the cGAS-STING pathway, prompting the production of type I IFN, which bolsters dendritic cell maturation and mediates T cell activation, thus igniting anti-tumor immunity." (PMID 39861694, 2025). "Next, knockdown of cGAS and STING in tumor models would have been useful to directly assess their functional impact." (PMID 41401057, 2025). "The study also discusses strategies for leveraging cGAS/STING signaling to enhance the efficacy of immunotherapies and address tumor-mediated immune suppression, providing insights into future directions for personalized cancer treatments." (PMID 39949780, 2025). "Preclinical studies have demonstrated synergistic antitumor effects of cGAS–STING agonists and ICIs across various tumor models, while early-phase clinical trials are exploring their safety and efficacy in patients." (PMID 41204180, 2025). "This approach achieved dual activation of the cGAS-STING pathway and reshaped the tumor immune microenvironment, significantly enhancing the activation of tumor-infiltrating CD8+ T cells." (PMID 41438738, 2025). "The reduced expression of cGAS, STING, and IFN-I proteins in MOC2 tumors highlights the importance of this pathway in modulating tumor aggressiveness and immune responsiveness." (PMID 40282455, 2025). "Given that CTX induces DNA damage and type I interferon (IFN-I), we investigated the role of host cGAS and STING in the anti-tumor effect of CTX in vivo." (PMID 40227734, 2025). "Our findings reveal that radiotherapy-induced cholesterol inhibits cGAS–STING signaling, facilitating tumor immune escape." (PMID 40355720, 2025). "Herein, the expression of cGAS‐STING pathway‐related protein (including pTBK1 and pIRF3) were further examined in 4T1 tumor cells by western blotting, and demonstrated a Mn2+ concentration dependent manner." (PMID 39792614, 2025). "Based on this, we have designed RMPs@Mn2+ hydrogel to efficiently amplify the cGAS-STING cascade of antigen-presenting cells (APCs) and promote T-cell priming and infiltration, thus resulting in tumor regression." (PMID 40052963, 2025). "Recent studies indicate that the cGAS-STING pathway plays a dual role in TNBC by modulating immune responses and the tumor microenvironment." (PMID 40567603, 2025). "The complexity of cGAS–STING signaling, coupled with tumor-intrinsic resistance mechanisms, an immunosuppressive TME, and the risk of exacerbated immune-related toxicities, presents formidable barriers to clinical success." (PMID 41204180, 2025). "To examine the influence of cGAS–STING activation of tumor cells on the efficacy of radiotherapy, we established a murine syngeneic tumor model using shNC MC38 or shSTING MC38 cells." (PMID 40355720, 2025). "Results indicated that metformin activated the cGAS-STING pathway and interferons in PBMCs, enhancing their anti-tumor capabilities." (PMID 40221409, 2025). "Together with the Mn2+‐mediated cGAS‐STING pathway to stimulate the immune response, substantial anti‐tumor immune effects can be achieved." (PMID 40405693, 2025).
tumor (continued). "CDN-NP ingested by tumor cells would be released again to activate immune cells, thereby activating cGAS-STING signaling and inducing a strong anti-tumor immune response." (PMID 40052963, 2025). "This review aims to target the cGAS-STING pathway to reprogram TAMs, thereby enhancing anti-tumor immunotherapy." (PMID 40075527, 2025). "DNA sensor, the cGAS-STING signal, is an essential innate immune signaling pathway that senses dsDNA to mediate tumor progression and prognosis." (PMID 40296918, 2025). "To further validate this hypothesis, we simulated cGAS activation with cGAMP or diABZI treatment while inducing a decrease in intracellular and ER pH through lactic acid treatment, which is abundant in the tumor microenvironment and known to lower intracellular pH levels." (PMID 40663398, 2025). "Strategies to modulate the TME aim to reshape its immune landscape and metabolic features to amplify cGAS-STING activation and restore anti-tumor immunity." (PMID 40052963, 2025). "The cGAS-STING pathway, in particular, in dendritic cells (DCs), has emerged as a critical intrinsic tumour-detecting mechanism." (PMID 40254425, 2025). "Suppressing DHODH led to pyroptosis in cancer cells and activated the cyclic GMP-AMP synthase (cGAS)-stimulator of interferon genes (STING) pathway, forming the basis for NK cell-induced anti-tumor immune responses." (PMID 41144149, 2025). "On the other hand, PRMT3-mediated inhibition of HSP60 methylation activates the cGAS/STING pathway, which enhances the anti-tumor immune response." (PMID 41583428, 2025). "By activating innate immunity, cGAS-STING signaling helps the immune system recognize and attack cancer cells, inhibiting tumor growth and improving patient outcomes." (PMID 39949780, 2025). "Studies indicate that cGAS and STING silencing can partially restrict the anti-tumor potential induced by DNA damage agents and programmed cell death 1 ligand 1 (PD-L1) antibody." (PMID 40296918, 2025). "This dsDNA activates DCs via the cGAS-STING pathway, increasing IFN-β secretion and enhancing NK/CTL-mediated tumor killing." (PMID 40521198, 2025). "For example, by promoting photothermal-enhanced copper deposition and activating the cGAS-STING signaling pathway, they can alter the immunosuppressive state of TNBC, enhance antitumor immune responses, and inhibit tumor growth." (PMID 40567603, 2025). "In fact, in mesenchymal stromal cells (MSCs), a group of cells that play a crucial role in tumor metastasis, the expression of ISGs, such as the chemokine CCL5, is upregulated alongside the induction of cGAS-STING signaling." (PMID 40565309, 2025). "Radiotherapy modulates the cGAS-STING pathway by inducing nuclear and mtDNA damage and remodeling the tumor immune microenvironment." (PMID 41189946, 2025). "These ions can freely penetrate cell membranes and increase the affinity of cGAS for double-stranded DNA to further activate the STING pathway, thereby stimulating the maturation of dendritic cells (DCs) and enhancing tumor-specific T cell responses." (PMID 40435257, 2025). "The balance between beneficial and detrimental outcomes depends on the duration and intensity of cGAS-STING activation, with chronic activation often leading to inflammation and tumor-supportive conditions." (PMID 40507791, 2025). "This environment, along with cGAS–STING inhibition, prevents immune cell infiltration and cytokine release necessary for an effective anti-tumor response." (PMID 39949780, 2025). "When comparing the HPSCC cell lines FaDu and 2A3 in vitro, differences were observed in the expression levels of DDX60 and RIG-I, while in vivo models differed in cGAS and DAI expression in tumor cells." (PMID 41401057, 2025). "EB@MPCM with spatiotemporal synergistic delivery system can effectively activate cGAS‐STING signaling pathway and realize in situ blockade of PD‐1/PD‐L1 axis at the time of maximal CTLs infiltration in tumor microenvironment (TME)." (PMID 39792614, 2025).
tumor (continued). "The cGAS and STING pathway is a critical cellular mechanism for detecting cytosolic DNA, leading to the activation of immune responses that can have both tumor-suppressive and tumor-promoting effects." (PMID 39949780, 2025). "(2022) demonstrated that gut microbial metabolites can interfere with radiotherapy-induced cGAS-STING pathway in DCs, subsequently weakening antigen presentation and T cell function, ultimately compromising the anti-tumor immune efficacy of radiotherapy." (PMID 41438738, 2025). "In summary, our findings revealed that PRMT1 knockdown inhibits the cGAS/STING pathway in GC, which produces type I IFNs to promote the polarization of M1-like macrophages in the tumor microenvironment." (PMID 40858547, 2025). "In the present study, a novel mechanism was revealed whereby PRMT5 inhibition promotes CPT‐11 sensitivity and synergistically induces a dMMR‐like state in MSS CRC, further activating the cGAS‐STING signaling pathway and boosting anti‐tumor immunity." (PMID 40344511, 2025). "The interplay between ferroptosis and cGAS-STING is pivotal: ferroptosis-driven ICD releases DAMPs (e.g., HMGB1, CRT), while Mn2+ amplifies cGAS-STING signaling to enhance type I interferon production, collectively inhibiting tumor growth and metastasis." (PMID 40846966, 2025). "cGAS acts as a catalyst to promote the synthesis of the second messenger 2′3′-looped GMP-AMP (cGAMP) and activates STING in tumor cells." (PMID 40356601, 2025). "Radiation induces DNA double-strand breaks, activating the cGAS-STING pathway, promoting type I interferon release, and enhancing tumor antigen presentation." (PMID 40236990, 2025). "The combination therapy induced robust anti-tumor immunity by activating the cGAS–STING pathway, leading to increased infiltration of CD8+ T cells into the tumor microenvironment, significantly enhancing the observed therapeutic efficacy." (PMID 40355720, 2025). "In the case of cancer, prolonged stimulation of cGAS-STING can also allow immune escape, thereby diminishing the effectiveness of immunotherapy or co-enhancing tumor function." (PMID 41007720, 2025). "Inhibition of this interaction permits cGAS activation and subsequent IFN‐I production that enabled cDC2 to support anti‐tumour immune responses." (PMID 40878038, 2025). "Lactobacillus strains induce cGAS/STING-dependent type I interferon production, activate dendritic cells, and recruit tumor-specific CD8 T cells to the TME." (PMID 41450920, 2025). "To verify the correlation between YAP1 and cGAS-STING, we used hepatocellular-specific Yap1 gene knockout mice to establish liver in situ tumour-bearing mice using DEN/TCPOBOP induction." (PMID 40918140, 2025). "The cyclic GMP-AMP synthase (cGAS)-stimulator interferon genes (STING) signaling pathway plays a crucial role in activating innate and specific immunity in anti-tumor immunotherapy." (PMID 40075527, 2025). "Secondly, activation of the cGAS-STING pathway leads to the release of chemokines, attracting effector T cells to the TME and ultimately enhancing the destruction of tumor cells." (PMID 40098962, 2025). "BIBR1532 combined with radiotherapy induces NSCLC cells to undergo iron death while activating the cGAS-STING pathway, facilitating the occurrence and development of anti-tumor immunity." (PMID 40166469, 2025). "Collectively, these findings suggest that the cGAS–STING pathway functions as a “double-edged sword” in bone oncology, with its effects determined by tumor type, immune context, and microenvironmental cues." (PMID 41415288, 2025). "The anti-tumor effects of CENPM knockdown were reversed by cGAS inhibition, confirming cGAS-STING involvement." (PMID 39949780, 2025). "The cGAS-STING pathway is vital in cancer immunotherapy, acting as a sensor for cytosolic DNA and triggering immune responses to detect and combat tumor cells." (PMID 39949780, 2025).
tumor (continued). "Activation of the cGAS–STING pathway enhances the infiltration and function of CD8+ T and NK cells, while tumour‐expressed PD‐L1 promotes immune evasion by inhibiting cytotoxic T cell activity." (PMID 41275427, 2025). "This reprogramming effect underscores the potential of targeting the cGAS-STING pathway as a therapeutic strategy to alter the TME and improve anti-tumor treatments." (PMID 40075527, 2025). "Second, H1975dnMCAK cells exhibited activation of cGAS–STING signaling and its downstream signaling, including tumor-promoting cytokine IL-6." (PMID 40136696, 2025). "STING inhibitor H-151 treatment significantly attenuated CAR-M-mediated tumor killing, confirming the synergistic roles of PI3K-AKT and cGAS-STING pathways in CAR-M innate immune functions." (PMID 41388305, 2025). "Under certain conditions, such as infection with nucleic acid from virus or dead tumor cells, KDM4B demethylates cGAS, untethering it from chromatin and allowing its translocation into the cytoplasm where it becomes activated." (PMID 40595456, 2025). "The cyclic GMP-AMP synthase (cGAS)-stimulator interferon genes (STING) signaling pathway is pivotal in activating both innate and specific immunity within anti-tumor immunotherapy." (PMID 40075527, 2025). "Under normal conditions, cGAS-STING activation leads to the production of IFN-I and inflammatory cytokines, enhancing anti-tumor immunity." (PMID 40052963, 2025). "Indocyanine green and doxorubicin plus ultrasound enhances the nuclear delivery of doxorubicin, induces tumor mitochondrial DNA oxidation, activates cGAS-STING signaling, and triggers anti-tumor T cell immunity." (PMID 41246345, 2025). "The detection of aberrant dsDNA triggers the activation of cGAS-STING signaling, resulting in the generation of IFN-I with anti-tumor effects." (PMID 40621423, 2025). "In EG7-OVA tumor-bearing mice, CpG/ZANPs exhibited remarkable tumor suppression through concurrent NLRP3 inflammasome activation and cGAS-STING-dependent type I interferon (IFN) production, effectively overcoming conventional alum’s Th1 response limitations." (PMID 40422849, 2025). "In our previous studies, we explored the roles of the cGAS‐STING signaling pathway and ginsenoside Rg3 in cancer therapy, highlighting their potential to enhance tumor immunotherapy and exhibit significant anticancer effects." (PMID 39834553, 2025). "The cyclic GMP-AMP synthase (cGAS) and stimulator of interferon gene (STING), highly expressed in human IBD, are potential anti-inflammatory and anti-tumor immunotherapeutic targets." (PMID 41959738, 2025). "We propose a model for the CD8+ T cell-dependent anti-tumor effect of CTX, which acts via cGAS and STING of host myeloid cells." (PMID 40227734, 2025). "The cGAS-STING pathway integrates innate and adaptive immune responses, serving as a pivotal “command center” for anti-tumor immunity." (PMID 41573551, 2025). "Since EO771 tumor cells are able to generate and export cGAMP spontaneously due to CIN, this need for host cGAS is interesting and has the following potential implications." (PMID 40227734, 2025). "This nanoplatform leverages triple tumor microenvironment (TME)-responsive mechanisms by GSH depletion, ROS generation, cGAS-STING activation, and an immune-driven ferroptosis loop." (PMID 40846966, 2025). "Beyond immune activation, cGAS-STING signaling directly induces tumor cell apoptosis, targeting genomically unstable cells and reinforcing immune-mediated tumor clearance." (PMID 40052963, 2025). "Concurrently, the resultant Mn2+ synergistically combines with DOX to co-stimulate the cGAS/STING pathway, potentially conferring anti-tumor properties." (PMID 40102383, 2025). "Chronic cisplatin exposure, especially in resistant tumor models, further amplifies cGAS/STING activation, increasing PD-L1, MHC class I, and calreticulin levels, making tumor cells more recognizable to immune cells." (PMID 39949780, 2025).